CXCL5 (C-X-C motif chemokine ligand 5)
Diseases named in the same sentence as CXCL5 in open-access papers (continued):
Sharing a sentence is not in itself a finding about the gene and the disease.
cancer (continued). "Overexpression of CXCL5 blocked H2O2-induced ROS in prostate myofibroblasts and cancer cells." (PMID 39765818, 2024). "Our findings illustrate that CXCL5, through HO-1, plays a role in antioxidation, and determine that the CXCL5/CXCR2/HO-1 pathway facilitates antioxidative communication between fibroblasts and cancer cells in the prostate." (PMID 39765818, 2024). "Indeed, various malignant tumor types, including NSCLC, exhibit high levels of CXCL5 expression compared to para-carcinoma or normal tissues." (PMID 39034411, 2024). "Some cytokines secreted by CAFs, such as CXCL5, TGF-β, hepatocyte growth factor(HGF), and pro-angiogenic factors, play an important role in promoting malignant transformation and the proliferation and invasion of cancer cells." (PMID 36759842, 2023). "Interestingly, interaction with BMMs, however, strongly induced neutrophil recruiting chemokines like Cxcl2, Cxcl3, Cxcl5, and Cxcl15 in classical PDAC cells, whereas release remained unchanged (9091) or increased much less (8513) in mesenchymal cancer cells." (PMID 37156840, 2023). "The cancer cell-derived EV were shown to modulate the dissemination pattern of metastatic cells and, in particular, MSC-EV have been seen to stimulate chondrocyte and synovial MSC migration via the CXCL5 and CXCL6/CXCR2 axes." (PMID 36076936, 2022). "Since CXCL5 mediates various cellular behaviors including cancer cell migration and metastasis, and the CXCL5-CXCR2 axis regulates organ-specific metastasis, including CRLM, we selected CXCL5 as a prototype to examine our hypothesis." (PMID 35027547, 2022). "ELR-positive chemokines, including CXCL1 and CXCL5, induce cancer cell migration and invasion; hence, we tested whether the secretion of CXCL1 and CXCL5 was downregulated in our cancer cell-macrophage cocultures, using the same experimental setup as before." (PMID 35998057, 2022). "However, immunosuppressive chemokines such as CXCL8, CXCL5, CXCL12, CCL2, and CCL22 were generally upregulated across the 13 cancer types." (PMID 34841742, 2022). "The combination of miRNA (miR-142-3p), mRNAs (CXCL5, KIF2A, RGS18, APL6IP5, and DAPP1), and snoRNAs (SNORD17, SCARNA12, SNORA6, SNORA12, SCRNA1, SNORD97, SNORD62, and SNORD38A) clearly distinguished the normal samples from the cancer group samples." (PMID 34827689, 2021). "Our results confirmed that circCTNNA1 played a pro-cancer role in CRC, which could serve as the ceRNA of miR-363-3p to promote the CXCL5 expression." (PMID 33640021, 2021). "The log2 (RPKM+1) values of five mRNAs were significantly lower in the cancer group than in the normal group regardless of pathology, while there was no significant change according to disease stage, except for CXCL5." (PMID 34827689, 2021). "Specifically, we identified CXCL5 as a key chemokine in collagen I-induced NET formation and show that the pharmacologic blockade of DDR1 effectively prevents collagen induction of CXCL5, subsequent NET formation, and cancer cell invasion." (PMID 34237033, 2021). "Bone marrow-derived macrophage efferocytosis of apoptotic cancer cells, but not apoptotic normal cells, resulted in increased gene expression of Cxcl1, Cxcl4, Cxcl5, and IL-6 inflammatory cytokines in comparison with peritoneal macrophages." (PMID 32059476, 2020). "A number of chemokines were significantly upregulated in cancer cell-educated BMSCs compared with non-educated BMSCs, including CXCL5 and CCL5." (PMID 31819035, 2019). "In conclusion, our study revealed that elevated expression level of CXCL5 might be an adverse prognostic marker for OS, PFS and RFS in cancer patients." (PMID 29743818, 2018). "Therefore, more relevant studies are warranted to investigate the effects of CXCL5 on DFS, PFS and RFS in human cancer." (PMID 29743818, 2018).
cancer (continued). "Mostly recruited following a CXCL5 gradient (whose human orthologues, CXCL1 and IL‐8, are expressed by cancer cells), these immunosuppressive cells could in turn promote EMT‐like changes in cancer cells, via multiple pathways comprising TGF, EGF, and HGF." (PMID 28599100, 2017). "In particular, growth-regulated protein (GRO), ENA-78/CXCL5, TIMP-2, and leptin were strongly up-regulated in malignant seroma, whereas IGFBP-1 (insulin-like factor binding protein-1), IL-3, IFN-γ, FGF-9 and IL-16 were down-regulated in malignant versus benign seroma fluid." (PMID 26361584, 2015). "The role of STAT1 and STAT3 pathways in the production of CXCL5 in cancer has not been well studied." (PMID 24274066, 2013). "In the cancer context, CXCL2 and CXCL5 have displayed pro-angiogenic properties." (PMID 21447198, 2011). "Considering the correlation between CXCL5 and CTH expression and its association with the metabolism regulation and cancer progression, CXCL5-CTH axis may orchestrates the overall metabolic programming and 3D cancer progression, which warrants further investigation." (PMID 40050422, 2025). "Notably, the recruitment mechanisms (CCL15 vs CXCL5/CXCL1/8) and effector molecules (VEGFC-dominant vs MMP9/VEGFA-cooperative) display cancer-type specificity, suggesting evolutionary selection for distinct molecular implementations of a conserved TANs-lymphatic metastasis principle." (PMID 40739091, 2025). "Mechanistically, cancer intrinsic TNFRSF14 phosphorylates FAK at Y397 and activates its downstream NF-κB signaling, which not only enhances the tumorigenicity of GBM cells, but promotes the recruitment of anti-inflammatory TAMs through elevating CXCL1 and CXCL5 secretion from GBM cells." (PMID 39085878, 2024). "But IL1RAP (p = 4.234 × 10−11), CXCL3 (p = 0), CXCL5 (p = 0), and CXCL6 (p = 0) gene expression levels had higher expression in ER-negative than ER-positive ones; whereas IL6ST was the only gene whose expression was higher in ER-positive cancer patients (p = 0)." (PMID 39201290, 2024). "Additionally, FJX1 expression was significantly and positively correlated with immunosuppressive genes (TGFB1 and IL-10), chemokines (CCR1 and CCR5), chemokines receptors (CCL2 and CXCL5), and immunosuppressive pathway-related genes (TFGB1 and WNT1), in most TCGA cancers." (PMID 37324001, 2023). "First, we did not reveal the mechanism by which the secretion of CXCL5 in cancer cells was upregulated by AB680 due to the lack of the substrate of CD73 enzyme in vitro, although we used an additional substrate in this study to mimic the increased AMP level in vivo." (PMID 37867243, 2023). "In addition to these chemokine receptors, chemokine ligands such as CXCL1, CXCL2, CXCL5, CXCL6, CXCL8, and CXCL9 have been also significantly correlated with poor survival and metastasis in several cancers by recruiting MDSCs and suppressing the antitumoral activity of CD8+ T effectors cells." (PMID 32719800, 2020). "CXCL5/CXCL6 are both chemokine proteins thought to play a role not only in chemotaxis, but angiogenesis and tumorigenesis in many cancer types." (PMID 32903405, 2020).
infection (142 papers, 2010 to 2026). The state of being infected such as from the introduction of a foreign agent such as serum, vaccine, antigenic substance or organism. "CXCL5 (ENA-78), a chemoattractant for neutrophils and several other types of immune cells, emerged as a hallmark of dormant infection." (PMID 41387890, 2025). "The protein encoded by Cxcl5 (epithelial cell-derived neutrophil attractant) is a chemokine that has been demonstrated to attract neutrophils at the site of infection." (PMID 37505851, 2023). "In conclusion, we identified a group of cytokines, including IL-17C, MMP-10, FGF-23, CCL23, FGF-19 and CXCL5 that are differentially regulated during asymptomatic and mild symptomatic infections and are known to be associated with tissue repair functions." (PMID 35479098, 2022). "The data on viral replication and proliferation suggest that CXCL5 deficiency facilitates pulmonary viral clearance to a certain extent during the late stage of infection." (PMID 34868067, 2021). "WT and CXCL5-/- mice gradually lost weight after infection, and the greatest weight loss (20%-30%) was observed at 7 to 9 days post infection (d.p.i.)." (PMID 34868067, 2021). "TP3 treatment caused a decrease in TNF-α, IL-6, and CXCL5 at the site of infection on days 1, 3, and 5; on the other hand, MRSA infection induced TNF-α and IL-6." (PMID 25992774, 2015). "CXCL5 signaling is associated with cellular proliferation and differentiation, and the aberrant expression of this chemokine can lead to a range of dysfunctional outcomes, potentially contributing to the incidence of infection and/or OP development." (PMID 35646907, 2022). "Indeed, genes within the IL-17 pathway including Cebpb, Tnf, IL-6, Cxcl1, Cxcl2, Cxcl3, Cxcl5, Cxcl10, and Ccl7 were shown to be up-regulated in both susceptible and resistant mice during infection." (PMID 29339782, 2018). "CXCL5 deficiency leads to increased B lymphocyte accumulation in infected lungs, contributing to an enhanced B cell immune response and facilitating induced bronchus-associated lymphoid tissue formation in the infected lungs during the late infection and recovery stages." (PMID 34868067, 2021). "Beyond CXCL5, our machine-learning approach highlighted several other novel candidates: PDGF-B, Galectin-1, CXCL11, ANGPT1, EGF, TIE2, MCP-2, and NOS3 that each outperformed CXCL5 in discriminating a dormant infection from uninfected joint replacements." (PMID 41387890, 2025). "One day after infection, the expression of Cxcl1, Cxcl2, Cxcl5, TNF-α, and IL-1β were 15 – 50-fold higher in lungs of Mki67WT mice exposed to hyperoxia when compared to Mki67WT mice exposed to room air." (PMID 40494897, 2025). "In the case of MHV-JHM infection, changes in expression (from 0% to 100%) were visible in IL-6, IL-18, IL-33, ENA-78 (CXCL5), GRO alpha (CXCL1), IP-10 (CXCL10), MCP-1 (CCL2), MIP-1 beta (CCL4), MIP-2 alpha (CXCL2), RANTES (CCL5), and TNF alpha." (PMID 40358160, 2025). "Synovial inflammatory proteomics show an increase in synovial CXCL5 associated with dormant infection (p = 0.011, t-test), suggesting the establishment of a chronic inflammatory state by the MPS during a dormant infection involved in neutrophil inhibition." (PMID 39563367, 2024). "The function of CXCL5 in vivo is to recruit immune cells, specifically neutrophils, to the site of infection." (PMID 36624683, 2023). "At 3 months after COVID-19 infection none of these proteins remained lowered, but at 18-24 months after infection CXCL5 was reduced again." (PMID 37868959, 2023). "Mice with previous Spn infection had faster bacterial clearance upon secondary infection in part to prolonged stability of the chemokine ligand CXCL5 transcripts by IL-17a resulting in more rapid neutrophil recruitment to the lung." (PMID 35646729, 2022).
infection (continued). "Infection led to robust induction of chemokine and interleukin genes, including Il1b, Il6, Ccl2, Ccl3, Ccl4, Ccl7, Cxcl1, Cxcl2, Cxcl5, Cxcl9, and Cxcl10, and related receptor genes, including Ccr1, Ccr4, Ccr5, Ccr5, Ccr7, Cxcr2, Cxcr5, Il1r2, and Il1rn." (PMID 35487885, 2022). "In contrast to our findings, CXCL5, which was also downregulated after infection in our study, was reported to be induced after in vitro SARS-CoV-2 infection of primary lung cells." (PMID 35479098, 2022). "With the infection of larval E. granulosus, there were higher expression levels of many inflammatory factors in splenic B cells, such as Cxcl5, Il1r1, S100a8, S100a9, and CD14, which form a complex network of immune regulation." (PMID 35548052, 2022). "We observed that increased susceptibility to infection was accompanied by increased neutrophil recruitment and IL-1, CXCL1, and CXCL5 levels in the lung homogenates." (PMID 36119114, 2022). "Mice with heightened levels of CXCL5 had increased neutrophil influx, better control of pulmonary burden and increased survival upon Spn infection." (PMID 35646729, 2022). "CXCL5 levels tended to be higher in BALF of Dnmt3bfl/flCc10Cre mice relative to control mice at 6 hours post-infection (P = 0.07); BALF CCL20 concentrations were similar in Dnmt3bfl/flCc10Cre and control mice." (PMID 33793661, 2021). "In the influenza virus infection mouse model described here, H1N1 infection induced CXCL5 production in infected lung during the acute infection period." (PMID 34868067, 2021). "It was found that Rufomycin 4–7 treatment significantly decreased the Mabs-R-induced gene expression of various proinflammatory cytokines and chemokines (Tnfa, Il1b, Il6, Cxcl5, Ccl2, and Ccl4) in BMDMs at 6 h post-infection (hpi)." (PMID 34447358, 2021). "In our study, cytokines, such as MIP-1α/β, RANTES/CCL5, MDC/CCL22, KC/CXCL1, and LIX/CXCL5 were upregulated after infection." (PMID 35126335, 2021). "Downregulation of the CXCL1/2/5-CXCR2 axis, as demonstrated in the CXCL5-/- infection mouse model and the CXCR2 blockade model, enhanced CXCL13 expression in infected lungs as soon as during the innate immunity stage." (PMID 34868067, 2021). "In the current study, the phenotype of CD64+ macrophages from CXCL5-/- infected mice was different from that of CD64+ macrophages from WT infected mice at the same infection time point (3 d.p.i)." (PMID 34868067, 2021). "In concordance with the transcript data, release of TNF, IL-8, and CXCL5 was consistent across all three infection conditions." (PMID 34006652, 2021). "BALF cytospin also demonstrated that neutrophil recruitment in infected lungs was significantly lower in CXCL5-/- mice than in WT mice during the early infection stage." (PMID 34868067, 2021). "Lung inflammation was assessed and compared between WT mice and CXCL5-/- mice during the early and late stages of infection." (PMID 34868067, 2021). "Of these, only CXCL5 was significantly induced in the vaccinated mice at both the early and late stages of infection." (PMID 34835277, 2021). "During udder inflammation, CXCL5 stimulates neutrophil-directed chemotaxis and influences the recruitment of lymphocytes, mast cells, granulocytes, and monocytes to the site of infection." (PMID 34663465, 2021). "Suggesting low systemic response, the blood of mice trained 9 weeks contained lower levels of a broad range of cytokines (IL-1β, IL-6, IL-10, IL-12p40, IL-17A, IL-18, IFNγ, TNF, CCL2 and CXCL5) 2 days after infection with L. monocytogenes." (PMID 34603295, 2021). "Histological scoring indicated that CXCL5-/- mice had less severe lung pathology than WT mice during the early infection stage." (PMID 34868067, 2021). "For this, we measured the expression levels of lung Cxcl1, Cxcl2 and Cxcl5 during infection with low or high doses of Mtb." (PMID 32203062, 2020).
infection (continued). "In the present study, we used a model of peritoneal sepsis; further work is needed to test the significance of GDF15 regulation on CXCL5-mediated neutrophil recruitments for other origins of infection, including lung bacteria pneumonia." (PMID 32424099, 2020). "GEM treatment (100 μM) of BMDMs dramatically suppressed the expression of a variety of inflammatory cytokines and chemokines (Il6, Il12p40, Il1b, Cxcl10, and Cxcl5) at 18 h after infection." (PMID 32155958, 2020). "CXCL5 is a chemoattractant responsible for mediating neutrophil recruitment during inflammation and infection and binds to CXCR2, which is present especially on the surface of immune cells, e.g. PMN49,50." (PMID 29615632, 2018). "For example, Cxcl5, while upregulated in all infected tissues, expression in diestrus tissue is lower at baseline and greater in infection as compared to estrus." (PMID 30134832, 2018). "CXCL5 expression was dependent on Rel A activity in EC and the peak of mRNA was observed after 9h post‐infection in their model." (PMID 29119707, 2018). "At 2 h post infection (p.i.), enhanced accumulation of mRNAs for Cxcl1, Cxcl2, Cxcl3, and Cxcl5, as well as Ccl3 and Ccl4, was evident (determined as differentially expressed using a 5% FDR)." (PMID 29636754, 2018). "In fact, several of the cytokines seen here are the same neutrophil chemokines (Cxcl5, Ccl4, Cxcl1) and T-cell chemokines (Cccl5, Cxcl10, Ccl17) that were highlighted in the infection effect analysis." (PMID 30134832, 2018). "On the other hand, it is long known that neutrophils are needed to efficiently cope with bacterial infections and CXCL5 was indispensable in several mouse models of infection." (PMID 29018439, 2017). "IFNg, IL6, KC (CXCL1) and LIX (CXCL5) were higher in the lungs of CB infected mice, indicating a heightened proinflammatory response in the CB infection." (PMID 28155887, 2017). "In humans, CXCL5, also named epithelial-derived neutrophil-activating peptide 78 (ENA-78) since is mainly expressed by epithelial cells, is among the most strongly upregulated genes in human gastric mucosa upon infection with H. pylori." (PMID 29057967, 2017). "The analysis of mRNA level of different cytokines revealed a different pattern of induction: IL-1β, IL-6, and IFN-γ are up-regulated in the antrum of mice at early time of infection, while CXCL5 and CXCL15 are induced only at 42 days." (PMID 29085807, 2017). "Curcumin suppressed CXCL5 expression to the same extent under both pre-NTHi and post-NTHi infection conditions." (PMID 27538525, 2016). "According to the results of our study, CXCL5 plays a central role as a converging point for upstream HI or infection and downstream neuroinflammation and BBB damage in the pathogenesis of white matter damage in the immature brain." (PMID 26738635, 2016). "Administering curcumin post-NTHi infection significantly suppressed NTHi-induced CXCL5 mRNA expression in vitro and in vivo." (PMID 27538525, 2016). "After infection of neonate mice by wild-typeSalmonella, a time-dependent increase in Cxcl2 and Cxcl5 mRNA expression was observed while mRNA expression was strongly reduced in enterocytes of adult mice isolated at day 4 after infection." (PMID 27408697, 2016). "We found that both Cxcl1 and Cxcl2 were significantly induced following infection in both WT and Card9-/- mice whereas Cxcl5 was poorly induced." (PMID 26679537, 2015). "In this study, IL-17 administration exacerbates neutrophil infiltration through the induction of CXCL1, CXCL2 and CXCL5 following S. aureus intramammary infection, whereas neutralization of the IL-17 by anti-IL-17 antibody reduced neutrophil infiltration." (PMID 26230498, 2015). "For example, the gene expression levels of the cytokines Cxcl1, Cxcl2, Cxcl5 and Cxcl17 was in agreement with the recruitment of neutrophils and DCs towards the site of infection." (PMID 25137043, 2014).